SIRT3 (sirtuin 3)
Diseases named in the same sentence as SIRT3 in open-access papers (continued):
Sharing a sentence is not in itself a finding about the gene and the disease.
cancer (continued). "Actually, miRNA is capable of controlling SIRT3 gene transcription in tumors to affect the progression of cancer." (PMID 35832551, 2022). "In conclusion, SIRT-3, as well as other sirtuins, seems to represent a target to be either activated or inhibited in a cancer-specific manner." (PMID 36080416, 2022). "It is important to note that SIRT3-specific treatment is very important in the research of different types of cancer." (PMID 35571098, 2022). "Nowadays, the presence or absence of organ and tissue metastases is used as a predictor of patient survival, thus, using SIRT3 to predict cancer metastasis patient survival needs further study." (PMID 35832551, 2022). "Sirt-3 is a key control for many pathways of cancer cell and has a prognostic value in HCC patients." (PMID 35776276, 2022). "Further characterization of the mitochondrial substrate protein of SIRT3 will contribute to a deeper understanding of cancer tumorigenesis." (PMID 35571098, 2022). "Based on the structure and biochemical function of SIRT3, a variety of SIRT3 inhibitors have been developed and applied for cancer treatment, but it has been challenging to develop high-efficiency inhibitors with few side effects." (PMID 35832551, 2022). "Several potential SIRT3 activators/inhibitors have been tested in different cell lines of cancer, but rarely in vivo." (PMID 35832551, 2022). "SIRT3 has far-reaching effects on nuclear gene expression, cancer, cardiovascular disease, neuroprotection, aging, and metabolic control.PARP6 enables protein ADP-ribosylase activity." (PMID 36439178, 2022). "A typical example is when SIRT3 expression inhibited the growth of cancer cells by promoting apoptosis and necroptosis." (PMID 36581622, 2022). "Accumulating evidence has recently demonstrated that SIRT3 has a key role in cancer, influencing cell death by targeting a series of key modulators and their relevant pathways in cancer." (PMID 35326523, 2022). "Si-RNA interference of SIRT3 compromised the anti-cancer effect of cis-platinum and RES combination." (PMID 35865961, 2022). "When we investigated the cytotoxic effect of anti-cancer drug (mTOR inhibitor, RSV) in SIRT3 OE cancer cell, it showed the number of cancer cell was significantly decreased in a dose-dependent manner." (PMID 35671305, 2022). "Butyrate acts as an inhibitor of SIRT3 to promote apoptosis of cancer cells via inducing high acetylation of PDHA1 to reverse the “Warburg effect”." (PMID 35832551, 2022). "On the contrary, in cervical cancer cells, the deacetylation of Acetyl-CoA Carboxylase by SIRT3 promotes lipid metabolism reprogramming, thus triggering cancer migration and invasion, displaying an oncogenic role." (PMID 34680344, 2021). "SIRT3 expression is associated with mitochondrial ROS levels and apoptosis induction in CRC cells treated with anti-cancer drugs." (PMID 34769108, 2021). "Accumulating evidence reveals a close link between SIRT3 and human diseases, including age-related diseases, cancer, cardiovascular diseases and metabolic diseases." (PMID 34776960, 2021). "Recently, it has been shown that Sirt3 play critical roles in cancer progression as well as chemoresistance 6,7." (PMID 34405009, 2021). "Similar to Sirt6 and Sirt7, Sirt3 was also related to DNA damage repair signaling pathway, which is one of core mechanism of cancer radioresistance." (PMID 34405009, 2021). "SIRT3 reportedly has a profound effect on nuclear gene expression, cancer, cardiovascular disease, neuroprotection, aging, and metabolic control." (PMID 34912814, 2021). "The silent information regulators SIRT1 and SIRT3 are members of thesirtuins protein family known to be involved in cancer genetics, aging and oxidative stress responses." (PMID 33687167, 2021).
cancer (continued). "SIRT3 plays key roles in mitochondrial dynamics, metabolism and energy regulation, and therefore their possible roles in the progression of cancer are being intensively investigated." (PMID 33937086, 2021). "2-methoxyestradiol (2-ME) is an anti-cancer drug, which has been found to bind to the typical and allosteric inhibitor binding sites on SIRT3 to inhibit its activity." (PMID 32724473, 2020). "We suspect that SIRT3 mediated SOD2 activity is specific to cancer microenvironment in DLBCL to protect cells from oxidative stress." (PMID 33273545, 2020). "SIRT3 has been shown to deacetylate and increase pyruvate dehydrogenase in cancer cells, which can increase both mitochondrial bioenergetics and glycolysis." (PMID 33178616, 2020). "Deacetylated ATP5A1 is involved in several mitochondrial functions, and SIRT3 is able to orchestrate the overall alterations in mitochondrial function, that is necessary for the growth of cancers." (PMID 32002124, 2020). "In cancer cells, similarly to the reduction of ATP production, the decrease of mitochondrial ROS formation is also significant, in which SIRT3 has been proved to play a pivotal role by the deacetylation and activation of superoxide dismutase 2 (SOD2) enzyme." (PMID 32117717, 2020). "Since the role of SIRT3 in cancer has been widely reported and is well summarized, in this part we mainly focus on how SIRT3 regulates its substrates to play a double-sided role in cancer." (PMID 32724473, 2020). "The ability of SIRT3 to regulate numerous cellular processes that are critical in cancer cell proliferation suggests it as a valid therapeutic target in the management of cancers, including cutaneous neoplasm." (PMID 33178616, 2020). "Although in our system SIRT3 functions as a pro-survival protein, anti-survival activity of this sirtuin were reported in other cancer cells." (PMID 33273692, 2020). "For example, SIRT3 (NAD-dependent protein deacetylase sirtuin-3, mitochondrial) expression is lower in cancer tissues compared to the pericarcinous tissues, and SIRT3 overexpression enhances mitochondrial functions while it inhibits cell growth." (PMID 32824856, 2020). "Overall, SIRT3 is capable of metabolic reprogramming and contributes greatly in the fate of cancers." (PMID 32724473, 2020). "Of note, SIRT3 can also inhibit cancer progression by deacetylation of its substrate to modulate proliferation and migration." (PMID 32724473, 2020). "Given the cytoprotective role of SIRT3 in multiple organs, inhibition of SIRT3 in certain cancers should be carefully evaluated and discussed." (PMID 32724473, 2020). "Through these strategies, a variety of SIRT3 inhibitors have been developed and they have shown good viability in a variety of diseases, especially in cancer." (PMID 32724473, 2020). "Based on numerous studies, SIRT3 has emerged as a metabolic regulator, and its potential role in cancer is being intensively investigated." (PMID 33178616, 2020). "For example, the most famous SIRT3 activator, Honokiol, exhibits some therapeutic effects in heart disease, inflammation-related diseases, cancer and metabolic diseases." (PMID 32724473, 2020). "Deacetylated ATP5A1 participates in several mitochondrial functions, and SIRT3 can orchestrate the overall changes in mitochondrial function, that are critical for cancer growth." (PMID 32002124, 2020). "Sirt3 expression is decreased in many human cancers, especially in 40% of human breast and ovarian cancers." (PMID 32765955, 2020). "The HDAC4, HDAC10, and SIRT3 copy numbers were recurrently lost in eight, six, and six cancer types, respectively." (PMID 30760718, 2019). "A major deacetylase in mitochondria, SIRT3, plays a crucial role in the regulation of cancer cell growth." (PMID 31817470, 2019). "SIRT-3 is a member of the mitochondrial sirtuin family, involved in the regulation of different mechanisms including metabolism, aging, and cancer." (PMID 30917505, 2019).
cancer (continued). "In certain cancer, in contrast, increased expression of SIRT3 was correlated with a worse clinical outcome." (PMID 31113446, 2019). "An NAD‐dependent deacetylase also known as Sirtuin‐3 (SIRT3) has been shown to regulate cellular metabolism in various cancers dynamically." (PMID 30993888, 2019). "Similar to the dual roles of SIRT3 in cancer biology, the prognostic value of SIRT3 in cancer is also dichotomous." (PMID 31113446, 2019). "One group observed a decrease in SIRT3 in murine lung tissue, while another observed an increase in SIRT3 protein in multiple cancer cell lines, including HCT116, U87, and MDA231, after 5 Gy ionizing radiation treatment in vitro." (PMID 30450031, 2018). "In the previous studies, it has been reported that the expression level of SIRT3 suppressed in several malignant tumor, including prostate, lung, and gastric cancers." (PMID 30094960, 2018). "Among the sirtuin members, SIRT3 has received much attention for its role in cancer genetics, aging, neurodegenerative disease, and stress resistance." (PMID 27686535, 2017). "There is one SNP (rs11574359), two genes (GPX4 and SIRT3) and one pathway (FoxO) that demonstrated age-related patterns of survival in cancer patients and will be discussed in turn." (PMID 29064820, 2017). "Collectively, these observations indicated that the anti-cancer effect of honokiol is mediated by activating Sirt3 expression." (PMID 28443025, 2017). "In vitro studies in human cancer cells revealed that overexpression of SIRT3 decreases the cell proliferation." (PMID 28197299, 2017). "Although SIRT3 has a potential role in cancer, it can also exert important control on other diseases." (PMID 27686535, 2017). "The role of SIRT3 in human cancer has been studied intensively to validate its effect on the disease state." (PMID 27686535, 2017). "For this reason, SIRT3 rises as a possible target to develop new therapeutic strategies against cancer." (PMID 28704962, 2017). "In these reports, SIRT3 expression correlates with a good outcome and a general increase in overall survival of cancer patients." (PMID 28704962, 2017). "In contrast, recent meta-analysis on 14 studies with 2165 cancer patients assessed the relation between SIRT3 immunohistochemical expression and their respective survival and clinical pathological characters." (PMID 28197299, 2017). "Loss of SIRT3 activity and hyperacetylation of SOD2 have been reported in many cancers including breast cancer, hepatocellular carcinoma, glioma and B cell malignancies." (PMID 29099803, 2017). "In some types of cancer, SIRT3 functions as a tumoral promoter, since it keeps ROS levels under a certain threshold compatible with cell viability and proliferation." (PMID 28704962, 2017). "SIRT3 was reported to be protective in several cancers like oral carcinoma, breast ovarian, and renal cancers." (PMID 28197299, 2017). "Taken together, Sirt3 mechanistically connects mitochondrial ROS, metabolism reprogramming and cancer progression." (PMID 27023612, 2016). "There have been concerns in recent years due to SIRT3’s emerging roles in cancer by regulating both cell death and survival." (PMID 27483432, 2016). "It inevitably made it difficult to draw a firm conclusion on the prognostic value of SIRT3 for Caucasian and cancer patients of other races." (PMID 27483432, 2016). "Consistent with the reported observation, we found that depletion of Sirt3 increases apoptotic activity in hypoxic cancer cells." (PMID 27270321, 2016). "Owing to its important role in cancers, the clinical relevance of SIRT3 expression to cancer progression and prognosis was noticed by the research community." (PMID 27483432, 2016). "In this study, we therefore performed a meta-analysis to evaluate the significance of SIRT3 expression in various cancers." (PMID 27483432, 2016).
cancer (continued). "Although the prognostic and clinicopathological features of SIRT3 expression in various cancers have been investigated by different research groups, however, inconsistent and opposing results can be observed." (PMID 27483432, 2016). "SIRT3, a class III histone deacetylase, has been implicated in various cancers as a novel therapeutic target." (PMID 27367026, 2016). "These experiments demonstrated a critical role of Sirt3 in regulating autophagy and apoptosis in cancer cells." (PMID 27270321, 2016). "In particular, SIRT3 opposes Warburg phenotype of both cancer and stromal cells and is downregulated in EMT-inducing cancer-associated fibroblasts (CAFs)." (PMID 27379175, 2016). "Downregulated and upregulated SIRT3 gene expression has also been observed in different cancer tissues, depending on the cell and cancer types." (PMID 27078640, 2016). "In humans, SIRT3 is found downregulated in several cancers, such as ovarian, breast, liver and gastric cancers, potentially via an increased mitochondrial oxidative stress and associated changes in cell metabolism." (PMID 27352213, 2016). "The correlation between SIRT3 expression and other clinical outcomes such as pathological differentiation across different cancers also remains controversial." (PMID 27483432, 2016). "Up to date, there are still no systematic reviews or meta-analyses discussing the role and clinical significance of SIRT3 in cancers." (PMID 27483432, 2016). "Silencing of Sirt3 expression also promoted apoptosis, and enhanced the sensitivity of cancer cells to hypoxia." (PMID 27270321, 2016). "In contrast, we found that Sirt3 is a positive regulator of autophagy in cancer cells under hypoxia, and inhibition of Sirt3 blunts the induction of mitophagy triggered by hypoxia." (PMID 27270321, 2016). "Recently, different results are reported regarding to SIRT3-mediated cell inhibition and proliferation, leading to the controversy of its roles in cancers." (PMID 26121691, 2015). "Recently, SIRT3 is found be able to deacetylate and increase pyruvate dehydrogenase activity in cancer cells, which can increase both mitochondrial bioenergetics and glycolysis." (PMID 26121691, 2015). "SIRT3 expression is lower or undetectable in an array of human cancers, including breast cancer, glioblastoma, colon cancer, and osteosarcoma, prostate and ovarian cancers." (PMID 26121691, 2015). "We then examined the expression of c-MYC in SIRT3-overexpressed cancer cell lines and control cells." (PMID 26317998, 2015). "Sirtuin 3 (Sirt3), one of the seven Sirtuins family members, plays critical roles in the progression of multiple cancer types." (PMID 24774224, 2014). "To test this possibility, we first investigated the possibility that Pfn1 interacts with SIRT3 in cancer cells." (PMID 25103363, 2014). "A survey of human tumors has shown that SirT3 protein expression is significantly decreased in tumors and deletion of at least one copy of SirT3 has been observed in 20%–30% of cancers." (PMID 25671107, 2014). "Pfn1-FLAG and SIRT3-HA fusion constructs were transiently introduced into the cancer cell line MIA PaCa-2." (PMID 25103363, 2014). "The discrepancy of Sirt3 expression between tumoral and peritumoral tissues was consistent with the results of other cancer studies." (PMID 24774224, 2014). "Based on the discrepancy in the current literatures, to clearly investigate the expression of SIRT3 and clinical significance in different types of cancer is of particular interests in developing SIRT3 to a promising therapeutic target in cancer treatment." (PMID 23272146, 2012). "Although plenty of literatures supported SIRT3 was involved in mitochondrial energy production and substrate oxidation, expression of SIRT3 in cancer has been controversial." (PMID 23272146, 2012).
cancer (continued). "Based on this report, we decided to investigate the effects of 4-OH-tamoxifen and deficiency of D-(+)-glucose or certain L-amino acids on the expression of mitochondrial SIRT3 in the human MDA-MB-231breast cancer cells in vitro." (PMID 21906315, 2011). "SIRT3 exhibits context-dependent roles in cancer, similar to SIRT1 and SIRT2." (PMID 41304967, 2025). "SIRT3 has been reported to play different roles in different cancer types." (PMID 40777993, 2025). "Future investigations should aim to dissect the tissue-specific functions of SIRT3, explore its molecular crosstalk with other apoptotic regulators, and evaluate its potential as a therapeutic target in aging-related disorders such as cancer." (PMID 40860195, 2025). "Thus, the NAD+–SIRT3/7–p21Cip1 pathway couples cellular metabolism and proliferation, supporting cancer cell proliferation." (PMID 39873399, 2025). "Studies have shown that the expression level of Sirt3 directly affects the repair ability of mtDNA after IR, and overexpression of Sirt3 increases the radiation resistance of cancer cells, whereas deletion of Sirt3 exacerbates apoptosis, which provides a new target for radiosensitization." (PMID 41287826, 2025). "Furthermore, sirtuin 3 (SIRT3) regulates cancer cell proliferation and proline metabolism by deacetylating the K228 site of the PYCR1." (PMID 41331125, 2025). "Our study showed that RCC1 could mediate the down-regulation of SIRT3 expression in KRAS-driven cancer cells." (PMID 41391757, 2025). "The roles of SIRT3 are diverse among different cancer types and genetic subtypes." (PMID 41391757, 2025). "Our study demonstrates that Arg-II promotes cancer progression including growth and malignancy such as metastasis-related process migration and DNA damages through a newly uncovered mechanism, i.e., suppression of Sirt3/enhancement of mtROS axis." (PMID 40177131, 2025). "Sirt3, a mitochondrial sirtuin, has been reported to exert antioxidant and anti-cancer effects." (PMID 40177131, 2025). "Although SIRT1 and SIRT3 are generally protective of normal tissue, inhibiting them in cancer cells could potentially enhance the effectiveness of chemotherapy." (PMID 41425553, 2025). "These exosomes contain specific miRNAs, such as miR-20a-5p and miR-421, which promote IL-6 production and pancrea1ic cancer progression, respectively, by regulating the SIRT3/H3K9ac/HIF-1α axis.The cargo of CAF-derived exosomes is crucial for their effectiveness in cancer progression." (PMID 40038745, 2025). "MDA-MB-231 research has not only helped to reveal the molecular basis of triple-negative breast cancer but also may provide a useful tool to reveal the part SIRT3 plays in cancer pathways." (PMID 38816444, 2024). "In cancers reliant on oxidative phosphorylation (OXPHOS), SIRT3 may promote growth, whereas it could suppress tumors in glycolytically dependent cancers." (PMID 38542426, 2024). "SIRT3 also plays a crucial role in the metabolic crosstalk between CAFs and PCa cells, where CAFs undergo Warburg metabolism under the influence of PCa cells, producing lactate that is taken up by cancer cells via monocarboxylate transporter-1 (MCT1)." (PMID 39796040, 2024). "Sirt3 is an epigenetic target from thefamily sirtuins deacetylaseswith rapidly growing interest in age-related, neurodegenerative, liver,kidney, heart, and metabolic diseases, as well as in cancer." (PMID 38261767, 2024). "Moreover, SIRT3 seemsto be protective in diseases such as age-related, neurodegenerative,liver, kidney, heart, and metabolic ones, as well as in cancer." (PMID 38261767, 2024). "Furthermore, innovative development tactics are required to design additional SIRT3 small molecule agonists for cancer therapy." (PMID 38773972, 2024). "Exploitation of SIRT3 activators for cancer treatment is still in the early stages." (PMID 38773972, 2024).